C4A (complement C4A (Chido/Rodgers blood group))
Description:
Precursor of non-enzymatic components of the classical, lectin and GZMK complement pathways, which consist in a cascade of proteins that leads to phagocytosis and breakdown of pathogens and signaling that strengthens the adaptive immune system. [Complement C4b-A]: Non-enzymatic component of C3 and C5 convertases. Generated following cleavage by complement proteases (C1S, MASP2 or GZMK, depending on the complement pathway), it covalently attaches to the surface of pathogens, where it acts as an opsonin that marks the surface of antigens for removal. It then recruits the serine protease complement C2b to form the C3 and C5 convertases, which cleave and activate C3 and C5, respectively, the next components of the complement pathways. Complement C4b-A isotype is responsible for effective binding to form amide bonds with immune aggregates or protein antigens, while complement C4b-B isotype catalyzes the transacylation of the thioester carbonyl group to form ester bonds with carbohydrate antigens. [C4a anaphylatoxin]: Putative humoral mediator released following cleavage by complement proteases (C1S, MASP2 or GZMK, depending on the complement pathway). While it is strongly similar to anaphylatoxins, its role is unclear. Was reported to act as a mediator of local inflammatory process; however these effects were probably due to contamination with C3a and/C5a anaphylatoxins in biological assays.
Synonyms: CO4; CPAMD2; C4S; C4; C4A3; C4A2; C4A4; C4A6; C4B; RG; C4AD
Tractability: Antibody: UniProt places it where antibodies can reach, with high confidence; its Gene Ontology location is reachable by antibodies, with high confidence; UniProt predicts a signal peptide or a membrane-spanning region. PROTAC: its protein half-life has been measured.
Gene: Protein-coding gene on chromosome 6 (31,981,991 to 32,004,877, forward strand). Ensembl gene ENSG00000244731.
Subcellular location: Secreted; Synapse; Cell projection, axon; Cell projection, dendrite; Secreted (C4a anaphylatoxin); Secreted (Complement C4b-A); Cell surface
Pathways (Reactome):
Immune System: Activation of C3 and C5; Initial triggering of complement; Regulation of Complement cascade
Metabolism of proteins: Post-translational protein phosphorylation; Regulation of Insulin-like Growth Factor (IGF) transport and uptake by Insulin-like Growth Factor Binding Proteins (IGFBPs)
Disease: Dengue virus activates/modulates innate and adaptive immune responses
Gene Ontology:
Molecular function: complement component C1q complex binding; protein binding; complement binding; endopeptidase inhibitor activity
Biological process: complement activation; complement activation, GZMK pathway; positive regulation of apoptotic cell clearance; inflammatory response; response to other organism
Cellular component: axon; blood microparticle; cell surface; dendrite; extracellular exosome; extracellular region; neuronal cell body; synapse; endoplasmic reticulum lumen; plasma membrane
Genetic constraint (gnomAD): Loss-of-function variants: 11 observed, 24.21 expected, observed/expected ratio (o/e) 0.45, 90% interval 0.28 to 0.75. The synonymous counts are far from expectation, so gnomAD's model fits this gene poorly and the ratio says little. Missense variants: 111 observed, 287.07 expected, observed/expected ratio (o/e) 0.39, 90% interval 0.33 to 0.45. Synonymous variants: 54 observed, 119.75 expected, observed/expected ratio (o/e) 0.45, 90% interval 0.36 to 0.57.
Homologues: Orthologues: chimpanzee C4A (98% identical), chimpanzee C4A (97% identical), pig C4A (81% identical), rat C4b (79% identical), mouse C4b (76% identical), mouse C4a (74% identical), tropical clawed frog c4a (39% identical), zebrafish c4 (33% identical), Caenorhabditis elegans tep-1 (17% identical), Drosophila melanogaster Tep2 (17% identical), Drosophila melanogaster Tep4 (17% identical), Drosophila melanogaster Tep3 (17% identical), and 1 more. Paralogues in human: C4B (99% identical), C3 (27% identical), C5 (24% identical), CPAMD8 (20% identical), A2M (20% identical), PZP (19% identical), A2ML1 (18% identical), CD109 (18% identical).
Diseases named in the same sentence as C4A in open-access papers:
C4A is named in the same sentence as 469 diseases in open-access papers, as found by Europe PMC text mining. Sharing a sentence is not in itself a finding about the gene and the disease. The quoted sentences say what the papers report.
systemic lupus erythematosus (196 papers, 2004 to 2025). An autoimmune multi-organ disease typically associated with vasculopathy and autoantibody production. "Early-onset SLE or lupus-like phenotypes have been associated with the deficiency of complement factors, including C1q, C1r, C1s, C2, C3, C4A, and C4B." (PMID 39660463, 2025). "Complete C4 complement deficiency involving both C4 isoforms (C4A and C4B) is rare and often presents as early onset of lupus-like illness." (PMID 38406130, 2024). "Systemic lupus erythematosus and type 1 diabetes are both linked to C4A deficiency, whereas schizophrenia and bipolar illness are linked to C4A overexpression." (PMID 36798127, 2023). "When either human C4A or C4B was expressed in a lupus-susceptible strain, mice expressing C4A developed less humoral autoimmunity than C4B-expressing mice." (PMID 35958588, 2022). "Deficiency of C4A is associated with systemic lupus erythematosus and type 1 diabetes mellitus, and its overexpression is associated with mental disorders such as schizophrenia and bipolar disorder." (PMID 32518534, 2020). "Low copy number of C4 VNTR was strongly associated with increased risk of systemic lupus erythematosus and was coupled with lower levels of plasma C4A, whereas high copy number of C4 was protective and was associated with higher levels of plasma C4A." (PMID 30060490, 2018). "The studies distinguishing homozygous C4 deficiencies have repeatedly reported association between homozygous C4A deficiency and systemic lupus erythematosus (SLE)." (PMID 29928053, 2018). "This region is highly susceptible to recombination events leading to diverse diseases; for example, systemic lupus erythematosus (SLE) is a consequence of C4A deficiency." (PMID 19448367, 2009). "Additionally, lower copy numbers of C4 and C4A are associated with an increased risk of developing lupus, further highlighting the genetic contribution of complement dysregulation." (PMID 40565360, 2025). "In addition, some studies have suggested an association of HLA-DR2, HLA-DR3, C4A, and C4B null complement alleles with drug-induced lupus." (PMID 36407159, 2022). "Lupus-like presentations have now been associated with inherited deficiencies in many classical pathway complement components, including C1q, C1r, C1s, C2, C3, C4A, and C4B." (PMID 29922296, 2018). "The pooled statistical results revealed that low C4 (<4) and low C4A (<2) GCNs could be risk factors for systemic lupus erythematosus (SLE) in Caucasian populations." (PMID 28205620, 2017). "Genetic variants resulting in non-expression of C4A and C4B genes (so-called “null” alleles, C4A*Q0 and C4B*Q0) are common in healthy European populations and have shown association with a number of diseases, most notably the autoimmune disease, systemic lupus erythematosus (SLE/lupus; MIM: 152700)." (PMID 21857912, 2011). "Although C4A and C4B share >99 % sequence identity, C4A has been suggested to have a primary role in immune complex clearance, greatly supported by the strong association between systemic lupus erythematosus (SLE) and low copy numbers of C4A." (PMID 27090374, 2016). "In particular, complete genetic deficiency of complement component C2 is a strong risk factor for monogenic systemic lupus erythematosus (SLE), and partial deficiencies of C2 and C4A are important risk factors for SLE and primary Sjögren’s syndrome." (PMID 40142826, 2025). "We demonstrated the diversities of C4A and C4B proteins and their gene copy number variations (CNVs) in healthy subjects and patients with autoimmune disease, such as type 1 diabetes, systemic lupus erythematosus (SLE) and encephalitis." (PMID 34764957, 2021). "As well as, Pathways related to C4A include complement and coagulation cascades, Pertussis, Staphylococcus aureus infection, Systemic lupus erythematosus." (PMID 31749922, 2019).
systemic lupus erythematosus (continued). "Lupus-prone families with primary defects of classical complement pathways (C1q, C1r/s, C2, C4A and C4B) revealed the importance of this pathway for lupus pathogenesis." (PMID 30744169, 2019). "Among these genes, the complement C4 gene with its isotypes C4A and C4B and the special feature of copy number variation has been repeatedly studied in lupus patients." (PMID 29050534, 2018). "Inherited (and acquired) deficiencies of the early classical complement components, C2, C4A, and C4B, encoded within the class III region, are associated with the development of lupus." (PMID 18437207, 2008). "By KEGG pathway analysis, six genes, i.e., C4A, C4B, FCGR2A, HLA-DMA, HLA-DRA, and HLA-DRB1, were enriched as the top 2 significant results in the pathways of Staphylococcus aureus infection (KEGG term hsa05322, FDR = 1.42E−05) and systemic lupus erythematosus (KEGG term hsa05150, FDR = 2.00E−04)." (PMID 34804021, 2021).
schizophrenia (116 papers, 2016 to 2026). A major psychotic disorder characterized by abnormalities in the perception or expression of reality. "The complement component 4 (C4A) has been linked to complement‐mediated synaptic pruning and cortical thinning in schizophrenia." (PMID 39680483, 2025). "In schizophrenia, genetic variations in complement components, particularly C4A, are associated with synaptic pruning abnormalities and disease susceptibility." (PMID 40867623, 2025). "For example, C4A, a complement component linked to synaptic pruning defects in schizophrenia, was active in the pons." (PMID 41394403, 2025). "Recent genetic studies have identified variations in C4A and C4B genes encoding complement component 4a and 4b within the major histocompatibility locus on chromosome 6 as a risk factor for schizophrenia." (PMID 39258226, 2024). "We directly genotyped 434 schizophrenia patients to determine their C4A and C4B copy number variants." (PMID 38341430, 2024). "Another signal of interest in this region is for decreased expression of C4A, the expression of which is associated with increased risk for schizophrenia." (PMID 38466119, 2024). "For example, the schizophrenia risk gene complement component 4 (C4) has C4A and C4B isotypes in human, but solely C4b in mouse." (PMID 36474001, 2023). "The C4 locus on chromosome 6 has a strong association with postmortem brain tissue in individuals with schizophrenia and expresses two isotype molecules, C4A and C4B." (PMID 36386965, 2022). "Nonetheless, given that schizophrenia genetic risk variants likely interact and converge on common biological pathways studying the effects of the C4A variant will give insight into pathology relevant to schizophrenia as a whole." (PMID 35600620, 2022). "Minor allele (G) carriers of rs204991, eQTL for C4A, having decreased risk for schizophrenia and lower imputed expression of C4A, had a better response to APDs." (PMID 35250027, 2022). "For instance, an high C4A gene dosage represents a relevant schizophrenia risk factor, while both C4A or C4B high copy number is related to Alzheimer’s disease." (PMID 34394006, 2021). "The C4 component is encoded by two different genes, C4A and C4B, exhibiting distinct relationships with schizophrenia risk." (PMID 33925147, 2021). "Using this procedure, predicted C4A gene expression was associated with risk of schizophrenia in an independent sample." (PMID 33653435, 2021). "Higher gene copy-number of C4A or a genetic deficiency of C4B, is a risk factor for neurologic or psychiatric disorder such as schizophrenia." (PMID 34764957, 2021). "For example, the strongest genetic risk association for schizophrenia is found in the loci near the complement C4 gene, and the levels of C4A expression predict the risk of the disease." (PMID 31906973, 2020). "Among these novel associations is Complement Factor 4A (C4A), recently implicated in schizophrenia through its role in synaptic pruning during postnatal development." (PMID 31306407, 2019). "We have genotyped the copy numbers of long and short forms of C4A and C4B gene variants in 129 European ancestry patients with schizophrenia or schizoaffective disorder." (PMID 31849639, 2019). "Noteworthy among these associations is Complement Factor 4A (C4A), recently implicated in the development of schizophrenia through its role as a mediator of synaptic pruning during postnatal development." (PMID 31306407, 2019). "A recent report suggested Complement 4 (C4A) gene copy numbers (GCN) as risk factors for schizophrenia." (PMID 30026462, 2018). "The most significant association with schizophrenia (P-SMR = 6.3 × 10− 8) was in the expression of C4A, encoding Complement C4A, which exhibited increased expression in association with risk variation." (PMID 30419947, 2018). "C4A is a gene with strong evidence of causal effect on schizophrenia risk via excessive synaptic pruning in the brain during development." (PMID 29739930, 2018).
schizophrenia (continued). "Similarly, since mice express a single C4 gene (C4b), introducing human C4A into mice helped uncover the mechanisms underlying the association between C4A and schizophrenia in humans." (PMID 40519165, 2025). "Particularly noteworthy is the finding that genetic polymorphisms of complement components C4A and C4B are significantly associated with various microbial environmental variables in schizophrenia patients, including a history of pathogen exposure and gut ecological imbalance." (PMID 41346597, 2025). "In cases of hyperactive pruning linked to C4A overexpression in schizophrenia, minocycline could be beneficial, provided that the timing of the intervention and the molecular profile of the patients are appropriately matched." (PMID 41169352, 2025). "Similarly, exciting recent work identified copy number variations in the genes encoding complement component 4 (C4A and C4B) as the currently strongest risk factor for the development of schizophrenia." (PMID 39022733, 2024). "C4 copy number varies and schizophrenia risk is increased in proportion to both the number of C4A alleles present and the expression level of C4A in the brain, leading to the suggestion that C4A more efficiently labels synapses to drive increased complement-mediated synaptic pruning." (PMID 38505993, 2024). "While genetic deficiency or depletion of C4A is associated with systemic autoimmune diseases, recent findings in neurologic disease suggested that high copy number of C4A or low copy number of C4B may be associated with schizophrenia." (PMID 34764957, 2021). "C4 came forward as a contributing factor in schizophrenia via genetic studies, and subsequent functional studies suggested that increased levels of C4A and its effector C3 were associated with increased synaptic pruning in schizophrenia." (PMID 33670154, 2021). "Interestingly, the strongest association with schizophrenia was found with alleles that increase expression of C4A." (PMID 32116493, 2020). "A recent example of the last case is provided by SNPs in the HLA region which tag variant haplotypes of C4, the gene for complement component four, the different haplotypes producing different levels of C4A expression associated with OR for schizophrenia risk of 1.3." (PMID 29564678, 2018). "Higher C4A gene copy number has been shown to be directly associated with higher levels of catabolites in the inferior frontal cortex, and lower levels of precursors in the inferior parietal lobule, suggestive of greater neuropil contraction in these regions, in patients with schizophrenia." (PMID 37041418, 2023). "Combining their evidence on the association of schizophrenia to C4, or C4A more specifically, with previous evidence on C1q-mediated postnatal synaptic pruning, provided a strong indication for the involvement of the classical pathway of the complement system in schizophrenia." (PMID 33670154, 2021). "In addition, C4A has been associated with roles in schizophrenia." (PMID 33816350, 2021). "While previous studies have implicated low copy number of C4A in autoimmune diseases, including systematic lupus erythematosus and rheumatoid arthritis, increased C4A was associated with schizophrenia susceptibility, possibly through its role in synaptic pruning." (PMID 31849639, 2019). "We found a large positive correlation between the number of C4A gene copies and the amount of C4 protein only in neutrophils and only in the schizophrenia group (Spearman's rho = 0.63, 95% BCa CI: 0.12 to 0.89, P = 0.012)." (PMID 42113976, 2026). "In patients with schizophrenia, significantly more complement protein was observed in EVs (namely C3, C4A, C4B, C4BPA, and C4BPB)." (PMID 40867623, 2025). "Others reported that C4A overexpression in mice induced enhanced microglial synaptic removal and schizophrenia-like behaviors." (PMID 38505993, 2024).